CXCR4 (C-X-C motif chemokine receptor 4)
Diseases named in the same sentence as CXCR4 in open-access papers (continued):
Sharing a sentence is not in itself a finding about the gene and the disease.
tumor (continued). "Importantly, CXCR4 inhibition prevented tumor metastasis in mice." (PMID 28245823, 2017). "Hence, targeting CXCR4 could lead to immune-mediated anti-tumor effects and develop a potential treatment regimen in the near future." (PMID 28753978, 2017). "Interestingly, p16INK4A-positive senescent cells in CXCR4-expressing tumour cells expressed CXCL12." (PMID 28489070, 2017). "Peptide R could enhance the efficacy of standard treatments such as radiation, chemo- and anti-VEGF therapies, known to up-regulate CXCL12 and CXCR4 as part of the escape program that favors tumor recurrence and dissemination at distance, restores the vasculature and promotes GAM recruitment." (PMID 27015814, 2016). "CXCR4 expression of tumor lesions could be confirmed by immunohistochemistry." (PMID 26843617, 2016). "Here we see that mesenchymal subtype of GBM, characterized by highly infiltrative tumor, has very high levels of CXCR4 and very low levels of GNG4 compared to the other subtypes which suggests that CXCR4 pathway might be a primary oncogenic signaling pathway in this type of tumor." (PMID 27382437, 2016). "Therefore, we believe that the reduction of EPC recruitment might be a major contributor to the change in tumor angiogenesis resulting from SDF-1/CXCR4 axis blockage." (PMID 27066828, 2016). "Therefore, it's reasonable if CXCR4 was subsequently low expressed in tumor tissues." (PMID 27835898, 2016). "We hypothesized that knocking down CXCR4 will decrease perivascular invasion of tumor cells." (PMID 27863376, 2016). "However, how CXCR4 was up-regulated in tumor cells is an issue of debate." (PMID 27007162, 2016). "In addition, both CXCR4 knockdown or AMD3100 treatment markedly reduced liver metastasis of SGC7901-exRUNX2 cells (P < 0.05), in association with improved survival of tumor bearing mice (P < 0.01)." (PMID 27007162, 2016). "Thus, suppression of the SDF-1/CXCR4 axis in a primary tumor environment might be a target for therapy in EC patients." (PMID 26851944, 2016). "Thus, the effect of plerixafor on the amount of available tumor cell CXCR4 receptors is probably both direct via receptor blockade and indirect via disruption of tumor-stroma cell interaction, preventing the stroma-induced increase in CXCR4 expression." (PMID 27307990, 2016). "Indeed, CAFs have higher expression of SDF-1α than those of normal breast tissue, and through this paracrine signaling, CXCR4 may promote local tumor cell proliferation, motility and invasion." (PMID 27556298, 2016). "Thus, the inhibition of the SDF-1α/CXCR4 signaling pathway or the recruitment of MDSCs to the tumor microenvironment may attenuate the progression of ER-negative BC." (PMID 27996037, 2016). "The CXCR4-CXCL12 axis is necessary for mediating the attraction of monocytic MDSCs into the tumor environment and PGE2 is important to regulation of CXCL12 production in cancer-associated fibroblasts and the cancer environment, and to enhancement of CXCR4 expression in Mo-MDSCs." (PMID 26758420, 2016). "However, according to our knowledge, our present study is the first to assess the serum concentrations of chemokine CXCL12 in relation to its specific receptor CXCR4 and classical tumor markers for EC (CEA and SCC-Ag) as well as marker of inflammatory states—C-reactive protein (CRP)." (PMID 27041792, 2016). "CXCR4-positive tumor cells might migrate toward distant organs in response to an SDF-1 gradient." (PMID 25557170, 2015). "Therefore, our results indicated that decreased miR-222 might promote the recruitment of macrophages to the tumor via the CXCL-12/CXCR4 axis." (PMID 26689540, 2015). "This study also demonstrated correlation between decreased expression VEGF-A and inhibition of tumor angiogenesis in both tumors and corresponding parent cells, suggesting Nef-M1 peptide may inhibits tumor angiogenesis by inhibiting CXCR4/VEGF signaling mechanism in CRC and BC." (PMID 26318034, 2015).
tumor (continued). "Therefore, the CXCL12/CXCR4/ACKR3 pathway could be investigated to target tumor growth, invasion, and proliferation of metastatic cells." (PMID 26441831, 2015). "This evidence further suggested CXCR4/CXCL12 could potentially promote tumor cell migration." (PMID 26560447, 2015). "In addition, RT-qPCR analysis from mice biopsies indicated that the expression by tumor cells of CXCR4 and ANGPTL4, two TGF-β target genes identified as key players to prime cancer cells towards the lungs, were both reduced when mice were treated with halofuginone." (PMID 26015407, 2015). "However, molecular mechanisms underlying CXCR4 expression in tumor cells have not been fully clarified." (PMID 25773070, 2015). "Thus, CXCR4 can drive epithelial to mesenchymal transition along with an upregulation of chemokine receptors and cytokines important in cell migration, lymphatic invasion, and tumor metastasis." (PMID 26576337, 2015). "In addition, CXCL12-derived peptides, including the N-terminal amino acid sequence KPVSLSYR, were used as carriers for gene delivery to CXCR4 expressing cells demonstrating that this technique may be useful in gene therapy of tumor cells expressing CXCR4." (PMID 26062132, 2015). "Hence, CXCR4 and CXCL12 form an important signaling axis between tumor cells and their microenvironment, with the interaction influencing the adhesion, migration and invasion of tumor cells, reflecting the strong association of CXCR4 with cancer metastasis." (PMID 25669980, 2015). "The combination of AMD3100 with bevacizumab further inhibited tumour growth, angiogenesis and fibrocyte-like cells recruitment, suggesting that CXCR4 inhibition could partially overcome the development of bevacizumab resistance by inhibiting the re-angiogenesis mediated by fibrocyte-like cells." (PMID 26635184, 2015). "Therefore, although it may not be critical for the formation of pre-metastatic niche, the SDF-1/CXCR4 axis is important for the recruitment of BMDCs to tumor microenvironment." (PMID 26416452, 2015). "Thus, targeting of CXCR4 by an appropriate therapeutic agent may be a means of controlling the tumor progression." (PMID 26318034, 2015). "Furthermore, CXCR4 can support tumor survival e.g. by promoting tumor vascularization." (PMID 26075720, 2015). "In these cases, increased cytoplasmic CXCR4 immunostaining might abrogate membrane expression, thus limiting tumor cell evasion, and, possibly, would be associated with nonmetastatic profile." (PMID 26161302, 2015). "Moreover, the SDF-1/CXCR4 signal axis could guide BMDCs to the premetastatic niche along with CXCR4+ tumor cells by SDF-1 gradient." (PMID 24587996, 2014). "Oncolytic vaccinia virus engineered to express a soluble antagonist of CXCR4 showed improved intratumoral virus replication, increased vascular disruption and a markedly reduced infiltration of the tumors by putative immune-suppressive and tumor promoting stromal cells." (PMID 28548066, 2014). "Before in vivo experiments, we evaluated whether the SDF1/CXCR4-dependent ECFCs recruitment into tumor mass could be an experimentally supported possibility, by performing ECFC in vitro chemoinvasion assay upon addition of CMs in the lower well of the migration chamber." (PMID 25003596, 2014). "Furthermore, using animal tumor models, CXCR4 antagonists have in vivo anticancer activity as well." (PMID 24883070, 2014). "Thus, CXCR4 RNAi and its antagonist can be used to inhibit tumor cell proliferation and growth." (PMID 24647809, 2014). "Interestingly, levels of CXCR4 in the tumor remained unchanged with treatment." (PMID 24674692, 2014). "Of all the tested markers, CD24, SSEA-4, SSEA-1 (CD15) CXCR4, E-cadherin and CD44v6 were expressed on the EpCAM positive population of the tumorigenic luminal-like xenograft cells, and thus candidates for defining functionally different luminal tumor cell subpopulations." (PMID 25419568, 2014).
tumor (continued). "Therefore, results may not be directly translated to solid tumors, but findings could give interesting insights into the potential role of drugs targeting CXCR4, as also shown in tumor animal models." (PMID 24904289, 2014). "In addition, we did not observe any other association between pattern of CXCR4 expression and other clinical findings such as age, gender, type of tumor, location, and histology." (PMID 24659999, 2014). "The stromal expressions of SDF-1 and CXCR4 did not prove to be associated with the tumor grade." (PMID 24416254, 2014). "Furthermore, soluble PC2CP increased the expression of genes that are known to favor tumor progression, such as VEGF (encoding vascular endothelial growth factor) and CXCR4 (encoding chemokine receptor CXCR4), demonstrating the critical importance of protein localization in cancer." (PMID 24713112, 2014). "CXCR4 influences self-renewal of malignant stem cells and is highly expressed in stem cell populations in patient tumours, which may account for its role in tumour progression and metastasis." (PMID 24583601, 2014). "Furthermore, blockade of CXCR4 inhibits tumor growth in a mouse model." (PMID 24728301, 2014). "Thus, selectively targeting both CXCR7 and CXCR4 in tumor vasculature may provide a robust anti-angiogenic approach to GBM treatment." (PMID 25084358, 2014). "The emerging role of CXCR4 in tumor-stroma cross-talk has a great therapeutic potential to deplete minimal residual disease and CSCs: the disruption of CXCR4-mediated tumor cell adhesion to stromal cells might sensitize residual cancer cells and stem cells to standard cytotoxic drugs." (PMID 24904289, 2014). "Interestingly, downregulation of CXCR4 expression resulted in reduced tumor growth in vivo." (PMID 24728301, 2014). "In addition, August Copenhagen Irish rat models implanted with tumor were used to examine the pathological changes and invasiveness of tumor in vivo, the expression of CXCR4 in tumor tissues and the expression of SDF-1α in the adjacent tissues to the HCC ones, using immunohistochemistry." (PMID 24912495, 2014). "Furthermore, we determined that, with the exception of classical prognostic factors such as gender and WHO grade, the expression of MIF or CXCR4 in tumor cells and the MIF expression in TILs were independent predictors of DFS and OS according to the multivariate Cox model analysis." (PMID 23497377, 2013). "In addition to the SDF-1/CXCR4 pathway enhanced by radiation-induced tumor hypoxia, the CSF-1/CSF1R signaling complex has also been recently implicated in recruitment of myeloid cells to growing tumors and in promoting the radiation-induced monocytic infiltration of tumors." (PMID 23882218, 2013). "Our results imply that CXCR4 has different biological functions in tumor cells and lymphocytes and that high CXCR4 expression in lymphocytes can induce the homing of immune cells to tumor microenvironments to improve the number of TILs and the anti-tumor immunity of TILs in ESCC." (PMID 23497377, 2013). "In addition, the expression level of CXCR4 in tumor tissues was also determined by ELISA assay." (PMID 23472074, 2013). "Furthermore, our results imply that peri- and postoperative inhibition of SDF-1α/CXCR4 signaling may reduce the risk of increased tumor growth in patients that have increased SDF-1α levels after wounding and have incompletely resected CXCR4 positive tumors." (PMID 23593347, 2013). "Moreover, CXCR4 overexpression correlated with poor prognosis in many tumor types." (PMID 24278179, 2013). "Furthermore, inhibition of CXCL12 and CXCR4 reduces tumor growth by blocking angiogenesis." (PMID 23555768, 2013). "In addition, efficient CXCL12 scavenging by 143B-LacZ-HA-X7 cells shown in vitro may at the primary tumor site also diminish CXCR4-mediated tumor growth promoting activity of CXCL12 in the human 143B OS cell line." (PMID 24040160, 2013).
tumor (continued). "Moreover, several lines of evidence suggest that the SDF1α/CXCR4 axis is involved in tumour progression and the development of distant metastases; this aspect has been highlighted particularly for breast carcinoma, which is characterized by the frequent appearance of bone metastasis." (PMID 23301946, 2013). "Furthermore, we also examined whether emodin can inhibit CXCR4 expression in tumor tissues by Western blot analysis." (PMID 23472074, 2013). "Thus, it could be hypothesized that a basal SDF-1 secretion leads to autocrine CXCR4 activation in some tumor cell culture." (PMID 22417013, 2012). "Interestingly, in the comparison of primary tumours with different capability to metastasize, primary samples that did not metastasize showed significantly lower expression of the chemokine receptor CXCR4 than primary samples from patients who later developed metastases (P < 0.001)." (PMID 22518090, 2012). "Therefore, we hypothesized that similar to normal neural stem cell niches, endothelial cell CXCL12 and tumor cell CXCR4 would play important roles in the biology of the GBM perivascular stem-like cell niche." (PMID 22427929, 2012). "The CXCR4/SDF-1 and chemokine (C-C motif) receptor 7/chemokine (C-C motif) ligand 21 (CCR7/CCL21) interactions may play key roles in accentuating the adhesion of tumor cells as the lung endothelium expresses a high level of SDF-1 and CCL21 to complement tumor cell expression of CXCR4 and CCR7." (PMID 22295241, 2012). "Thus, SDF-1/CXCR4 system seems to play a tumorigenic in feline mammary gland malignancy and in vitro cultures from these tumour samples may represent an experimental model to investigate the biological and pharmacological role of this chemokinergic axis." (PMID 22417013, 2012). "Therefore, K5 may suppress tumor pulmonary metastasis through inhibiting SDF-1α-CXCR4 chemotaxis movement and down-regulation of VEGF." (PMID 23300882, 2012). "The finding that tumor-associated endothelial cells express high levels of CXCL12 supported the hypothesis that this characteristic feature of GBM would involve CXCR4." (PMID 22427929, 2012). "Expression of membrane receptors such as CXCR4, a Gi protein-coupled receptor for the ligand CXCL12/stromal cell-derived factor 1α (SDF-1α), has been associated with increased proliferation, invasion and migration in GBM as well as in several other tumors and tumor cell lines." (PMID 21489226, 2011). "Moreover, it was shown that concomitant and high expression of CXCR4 and VEGF is a strong and independent predictor of early distant relapse in CRC and recent evidence indicates that CXCR4 may also play a role in tumor angiogenesis of CRC." (PMID 21349176, 2011). "Furthermore, this allows to retain the CXCR4 promoters as it exhibits high activity in tumor cells." (PMID 22022379, 2011). "Alongside testing the effects of plumbagin experimentally in various tumor cells, we also tested the hypothesis of plumbagin-mediated NF-κB inhibition as the key reason for the reduction in CXCR4 and other metastatic genes, in a virtual, predictive, tumor cell system." (PMID 21880153, 2011). "While the importance of CXCR4 in several normal tissue processes may complicate the therapeutic inhibition of this receptor, CXCR4 remains an extremely attractive therapeutic target to disrupt tumour metastasis." (PMID 22128892, 2011). "Therefore, metastasis of CXCR4+ tumour cells might be driven specifically to these organs through the SDF1-CXCR4 axis." (PMID 21342498, 2011). "In addition, high levels of CXCL12 in the tumor microenvironment may disrupt the CXCR4 driven chemotactic response of tumor cells towards CXCL12 expressing tissues such as bone and lung." (PMID 20849618, 2010). "CXCR4 may play an essential role in metastasis and, indirectly, earlier stages of tumor growth." (PMID 21179547, 2010).
tumor (continued). "Collectively, these data indicated that the specific interactions of SDF-1 with their receptor CXCR4 that expressed on mammosphere cells are likely to occur in tumor-stromal niches, and these interactions may be responsible for the proliferation of CD44+CD24- cells." (PMID 20569497, 2010). "The regulation of CXCR4 surface expression by 5T4 molecules may provide a new way to control response to the chemokine CXCL12 in normal circumstances but could be selected to advantage the spread of a tumor from its primary site." (PMID 20376365, 2010). "However, in that study, CXCR4 knockdown was also found to inhibit primary tumor growth." (PMID 20849618, 2010). "However, CXCR4 expression was observed to be related to tumor diameter (P > 0.05)." (PMID 21110890, 2010). "Notably, Cidofovir pre-treatment markedly abrogated both lung adhesion and invasion of TC-1 cells, completely in 4/6 mice, and in the two remaining mice, only two small microscopic metastatic foci were present 15 days after injection (both comprising 1–2 CXCR4+ tumor cells (***P<0.01)." (PMID 19325708, 2009). "Indeed, SDF-1 secretion by bone morphogenetic protein-2 increased tubular formation of microvascular endothelial cells and recruiting endothelial progenitor cells, and stimulated tumour growth directly, acting through CXCR4, which is expressed by carcinoma cells." (PMID 19773759, 2009). "Moreover, CXCR4 expression in squamous cell carcinoma of the head and neck could be used to identify tumor cells with increased metastatic potential." (PMID 19563666, 2009). "Therefore, further understanding the molecular mechanisms that are involved in the regulation of CXCR4 expression on tumor cells could lead to potential targets to modify the expression of CXCR4 and impact on metastases." (PMID 19563666, 2009). "In addition, there was little evidence of CXCR4 immunolocalization on host responding cells, such as tumor-associated macrophages, fibroblasts and endothelial cells." (PMID 19563666, 2009). "Thus, identifying cells with increased CXCR4 expression may be useful to predict the metastatic potential of a tumor and provides a mechanism for inhibiting tumor progression." (PMID 19563666, 2009). "Furthermore, CXCL12 can promote cancerdissemination indirectly by enhancing the vascular supply, since theCXCL12/CXCR4 axis may also promote tumor angiogenesis." (PMID 18779872, 2008). "In addition to tumor cells, CXCR4 staining was also observed in inflammatory cells." (PMID 19025611, 2008). "Moreover, CXCR4-positive tumour cells could migrate toward distant organs in response to SDF-1 gradient." (PMID 19002187, 2008). "The relatively low standard deviations within the three corresponding tumour cores from different positions of the tumour on the tissue microarray (the mean of the standard deviations over all patients equals 0.22) points to a low variability of cytoplasmic CXCR4 expression within one tumour." (PMID 17245339, 2007). "Therefore these findings suggest that tyrosine kinase receptor activation and/or a response to hypoxia, leading to increased HIF-1α, is critical for the regulation of the expression of CXCR4, and may represent a general scheme in tumor metastasis." (PMID 17083723, 2006). "Most recently, CXCR4 has shifted into focus as it might play an important role in tumour spreading." (PMID 16819541, 2006). "While our data and other studies have suggested the important role of CXCL12/CXCR4 biological axis in organ-specific tumor metastasis, studies have also suggested that CXCL12/CXCR4 may be implicated in promoting angiogenesis, tumor cell proliferation and survival." (PMID 17083723, 2006). "Se@A&F induces CAFs' inactivation and remodels the tumor microenvironment by down-regulating CXCR4 expression on CAFs' surface and inhibiting the CXCL12/CXCR4 signaling axis." (PMID 41328341, 2026).